TSLP (thymic stromal lymphopoietin)
Diseases named in the same sentence as TSLP in open-access papers (continued):
Sharing a sentence is not in itself a finding about the gene and the disease.
tumor (132 papers, 2011 to 2025). "TSLP is produced mainly by cancer‐associated fibroblasts (CAFs) in response to tumour‐derived cytokines and promotes Th2 polarisation via DCs, facilitating tumour progression." (PMID 40899118, 2025). "IL4 derived from basophils, and cancer-associated fibroblast-secreted thymic stromal lymphopoietin induce tumor infiltration of Th2 cells and promote Th2 inflammation, which is related to the poorer survival in patients with PAAD." (PMID 36975441, 2023). "On one hand, TSLP and Th2 immunity has been implicated in promoting tumor progression and metastasis." (PMID 36467403, 2022). "TSLP is responsible for the expansion of regulatory T cells and initiates T helper 2 responses in the tumor which are associated with worse survival prognosis." (PMID 36550535, 2022). "Th2 cell immunity, stimulated by thymic stromal lymphopoietin, caused the epigenetic reprogramming of the tumor cells, activating mammary gland differentiation and suppressing epithelial–mesenchymal transition." (PMID 35657353, 2022). "Safety of anti-TSLP must continue to be monitored in the long-term treatment both in terms of susceptibility to infections and neoplasms, even if it has been proven safe and well-tolerated in clinical studies." (PMID 34608100, 2021). "In turn, TSLP was secreted by cancer-associated fibroblasts (CAFs) activated by IL-1α and IL-1β, which are products of cancer cells and tumor cell-conditioned macrophages." (PMID 33022971, 2020). "TSLP caused the release of CCL17 by tumor cells with recruitment of eosinophils that in turn induced proliferation and restricted tumor cell apoptosis through up-regulation of Ki-67 and Bcl-2, respectively and of proangiogenic factors." (PMID 33042121, 2020). "An increased proportion of ILC2s have been also found in pancreatic adenocarcinoma where tumor cells and tumor cell-conditioned macrophages produce IL-1α and IL-1β favoring TSLP secretion by cancer-associated fibroblasts." (PMID 33233582, 2020). "The expression of TSLP is significantly associated with tumor development and metastasis; knockout TSLP expression can almost completely prevent cancer progression and lung metastasis." (PMID 31885639, 2019). "The expression of TSLRP and IL-7Rα and the production of TSLP isoforms should be investigated in both human primary macrophages and tumor-associated macrophages." (PMID 30057581, 2018). "The involvement of TSLP in tumor growth is also supported by several murine experimental studies, in which tumor growth was inhibited in TSLP-deficient hosts." (PMID 30214685, 2018). "TSLP produced by either tumor cells or cancer-associated fibroblasts was important for Th2 cell differentiation and intratumoral infiltration, allowing a permissive environment for the growth and metastasis of these tumors." (PMID 26919238, 2016). "It would be interesting to study specific mechanisms underlying TSLP-TSLPR signaling that influence tumor development in different cell types in the future." (PMID 26919238, 2016). "The authors propose amechanism whereby tumor cells induce the release of thymic stromal lymphopoietin (TSLP) fromcancer-associated fibroblasts (CAFs) which subsequently activates tumor antigen-loadeddendritic cells." (PMID 22969725, 2012). "However, systemic TSLP induction from the skin causes an effective CD4+ T cell-mediated anti-tumor immune response at the site of developing cancer in the breast." (PMID 35432341, 2022). "In the majority of studies TSLP-dependent Th2 inflammation was associated with tumor-promoting functions; however, in mouse models of breast and skin carcinogenesis, Th2 cell polarization was associated with tumor-suppressive functions." (PMID 33042121, 2020). "TSLP and/or its receptor has been shown to be expressed in several tumor types, where TSLP expression is associated with functional activities that can be associated or not with the induction of a Th2-prone tumor microenvironment, i.e., Th2-dependent and Th2-independent mechanisms." (PMID 33042121, 2020).
tumor (continued). "Additionally, in the humanized mouse model, anti-TSLP controlled tumor development and was associated with reduced capacity of tumor infiltrating T cells to produce IL-13." (PMID 21281484, 2011). "Thus TSLP-promoted GATA3+ Tregs may also exert their immunosuppressive function through their crosstalk with tumor-associated DCs or myeloid-derived suppressor cells (MDSCs)." (PMID 36107619, 2022). "Thus, these analyses suggest that, in addition to its long-recognized Th2 promoting role, TSLP may have a role in tumor-associated Treg response." (PMID 36107619, 2022). "To further investigate the role of direct TSLP signaling to CD4+ T cells in the establishment of TSLP-mediated tumor protection in the skin, we utilized CD4+ T cell transfer to TslptgTslpr–/– (TslprKO) animals." (PMID 39744942, 2025). "In another study, the expression of TSLP examined by immunohistochemistry was higher in cancer tissue compared to non-tumor sites." (PMID 40873585, 2025). "In this model of inflammation-driven epithelial carcinogenesis, TSLP plays a key role in the promotion of epithelial hyperplasia and tumor growth." (PMID 40873585, 2025). "Future research should focus on elucidating the molecular pathways involved in the pro-tumor and anti-tumor effects of TSLP." (PMID 40787610, 2025). "TSLP can promote tumor growth by acting as an antiapoptotic agent, inducing B regulatory cells, inhibiting type 1 antitumor immunity and promoting metastasis." (PMID 39962262, 2025). "To investigate the mechanism by which TSLP induction in the skin leads to tumor protection, we subjected K14-Tslptg/+ (Tslptg) mice that overexpress TSLP in skin keratinocytes to a skin carcinogenesis protocol." (PMID 39744942, 2025). "Using a xenograft mouse model, the authors reported that peritumoral administration of TSLP reduced tumor growth." (PMID 40873585, 2025). "The authors concluded that upregulation of epidermal TSLP can generate anti-tumor CD4+ T cell response in a Th2 inflammatory microenvironment." (PMID 40873585, 2025). "In this study, we further showed that calcipotriol-induced TSLP activates Th2 cells to release IL-4, which in turn promotes IL-24 production by TAMs, resulting in tumor cell apoptosis." (PMID 39782693, 2025). "Our present findings demonstrate that calcipotriol-induced TSLP also leads to the activation of CD4+ Th2 cells that promote tumor suppression during late-stage tumor progression." (PMID 39782693, 2025). "TNF-α and IFN-γ present in supernatants of TSLP-activated CD4+ T cells were required for PyMt tumor suppression." (PMID 40873585, 2025). "The protumorigenic role of TSLP in PDAC was extended by showing that TSLP levels are detected in situ in tumor cells and systematically in advanced cancer patients." (PMID 40873585, 2025). "CD4+ Th2 cells are necessary to establish tumor protection in response to TSLP in the skin, and this protective effect persists in the absence of CD8+ T or B cells." (PMID 39744942, 2025). "Th2 cells and eosinophils produce IL-8 and VEGF in response to TSLP and promote angiogenesis, aiding tumor growth." (PMID 39962262, 2025). "In contrast, several studies indicated an anti-tumor activity of TSLP, in particular, in skin squamous-cell carcinoma." (PMID 39201498, 2024). "Expanding research into the role of TSLP in different tumor types is urgently required to inform the application of anti-TSLP therapies in cancer." (PMID 38566968, 2024). "It has been reported that tumor cells can produce TSLP, known for its ability to induce DC to express OX40 ligand, a molecule that directs the generation of Th2 cells." (PMID 38557942, 2024). "As we mentioned in the introduction, one of the mechanisms through which TSLP, produced by tumor cells, contributes to immunomodulation is by promoting a Th2 profile in the tumor microenvironment." (PMID 38557942, 2024). "Elevated levels of angiogenic mediators such as VEGF-A and TSLP have been observed in tumours with higher oxidative phosphorylation levels." (PMID 39682192, 2024).
tumor (continued). "Here, we were able to determine that both human cell line U251 and tumor cells obtained from the biopsy of a patient with GBM (GBM-b) express TSLP when activated with EGF, a crucial growth factor prevalent in this tumor microenvironment." (PMID 38557942, 2024). "In summary, our findings indicate the presence of TSLP in GBM tumor cells suggesting a potential role as a modulator of neutrophil physiology in the tumor microenvironment." (PMID 38557942, 2024). "The Th2 response, as mainly represented by thymic stromal lymphopoietin (TSLP), causes epigenetic reprogramming of tumor cells, activating mammary gland differentiation and suppressing the epithelial‐mesenchymal transition." (PMID 38389406, 2024). "CAFs are a relevant cell population in the PDAC stroma that express IL-1R1, and when stimulated with IL-1α and/or IL-1β, they secrete several pro-tumor cytokines, including TSLP, which is responsible for pro-tumor Th2 inflammation in PDAC." (PMID 39125655, 2024). "On the other hand, denoting the importance of TSLP in the tumor microenvironment, we observed that TSLP protected neutrophils from apoptosis when cultured in the presence of tumors cells." (PMID 38557942, 2024). "On the other hand, we observed a significant increase in IL-8 production when PMNs were cultured with TSLP, both neutrophils alone and those co-cultured with tumor cells." (PMID 38557942, 2024). "Our results demonstrate that the tumor produces TSLP when stimulated with epidermal growth factor (EGF) in both the U251 cell line and the GBM biopsy (GBM-b)." (PMID 38557942, 2024). "TSLP expression level exhibits a significant increase in different tumor samples compared with normal tissues, including GBM tumors." (PMID 38557942, 2024). "TSLP directly stimulates keratinocyte activation in AD and tumor cell growth in CTCL, inducing a Th2-dominant tumor environment." (PMID 38398754, 2024). "The expression of TSLP when stimulated with EGF in U251 cell line and GBM-b cells suggests a potential contribution of GBM to the immunomodulation of the tumor microenvironment, through the production of TSLP, in line with previous reports in different tumors." (PMID 38557942, 2024). "In ICB + CIS cases with the highest intra-tumoral eosinophil penetration, IL-33 and then TSLP were the most increased cytokines in the blood and tumor." (PMID 37587450, 2023). "To determine the effects of TSLP on the histopathological progression of lung tumors, we utilized a grading system based on the defined KrasG12D tumor progression in the lung." (PMID 35565302, 2022). "Exposure to specific skin pathogens can enhance the expression of thymic stromal lymphopoietin, which can induce the differentiation of primitive T cells into Th2 cells and Th17 cells, mediating allergic inflammation of the skin." (PMID 35651728, 2022). "Previous studies have shown that TSLP act directly on tumor cells and provide anti-apoptotic signals sufficient to drive tumor growth." (PMID 36467403, 2022). "Nevertheless, further studies involving TSLP/TSLPR blockade combined with therapeutic options such as MAP kinase inhibitors (targeting tumor cells) or immune checkpoint therapies (targeting immune cells) are required." (PMID 36107619, 2022). "Recently, it was reported that large amounts of thymic stromal lymphopoietin (TSLP) are released by keratinocytes in lesioned skin samples of AD patients, an effect which leads to a considerable degree of inflammation and skin damage." (PMID 36543921, 2022). "TSLP also has an important role in cancer, and the pro- or anti-tumor effect is dependent on the type of tumor." (PMID 35874683, 2022). "While we show that TSLP expression by keratinocytes is likely induced by signals derived from tumor cells, the molecules involved remain to be determined." (PMID 36107619, 2022).
tumor (continued). "This work establishes that systemic TSLP induction activates a tumor antigen–specific Th2 cell immunity, which has a dominant role in suppressing the early stages of breast carcinogenesis." (PMID 35657353, 2022). "TNFα and IL-1β from tumor cells enable activation of CAFs to produce thymic stromal lymphopoietin (TSLP), which promotes Th2 polarization via DC conditioning." (PMID 36230914, 2022). "TSLP induction leads to a massive T cell infiltration into and lymphoid aggregate formation in the tumor-bearing lungs." (PMID 35565302, 2022). "TSLP has been described to have a pro-tumor effect and can drive tumorigenesis both directly and indirectly." (PMID 36467403, 2022). "To examine the role of TNF-α and IFN-γ in TSLP-induced PyMt tumor suppression in vivo, we implanted PyMt cells in Tslptg mice and blocked TNF-α and IFN-γ using blocking antibodies." (PMID 36467403, 2022). "We find that TSLP induction not only suppresses lung tumor initiation as demonstrated by lower tumor counts in mice expressing the Tslp transgene but also results in the development of smaller, more differentiated tumors." (PMID 35565302, 2022). "Although CD8+ T cells did not increase in the Tslptg tumors, it is possible that CD8+ T and natural killer cells contributed to the observed tumor suppression phenotype in response to TSLP induction as TSLP receptor is broadly expressed on immune cells." (PMID 36467403, 2022). "TSLP, at baseline level, has been shown to act directly on tumor cells and induce anti-apoptotic Bcl-2 expression." (PMID 36467403, 2022). "TSLP exerts its dominant anti-tumor effects through the induction of CD4+ Th2 cell immunity in the early stages of keratinocyte cancer development." (PMID 35432341, 2022). "A similar skin cancer model also demonstrates that TSLP enables Th2 formation which exerts an anti-tumour effect and improves tumour surveillance." (PMID 33401460, 2021). "Showing similar distribution as in the previous series, TSLP exhibited downregulation when comparing its log transformed levels in tumor vs. control (p = 0.001)." (PMID 33846436, 2021). "By contrast, few studies have pointed to an anti-tumor role for TSLP in mouse models and in human cancers." (PMID 34440780, 2021). "Of these, TNF-α, IFN-β, TSLP, and sVCAM-1, identified to be elevated in haematological cancers, are also known tumour-promoting factors." (PMID 34830872, 2021). "Th2 cytokines have been reported to show tumor-promoting effects in some solid tumors, and among these cytokines, IL-13 and thymic stromal lymphopoietin (TSLP) are shown to be directly involved in the progression of CTCL." (PMID 34884736, 2021). "It was also found that TSLP overexpression in the skin resulted in tumorigenesis resistance, thus confirming the tumor-suppressive effects of TSLP in the skin." (PMID 34306760, 2021). "One of the Th2 inflammatory pathways favoring tumor protection in BC relies on the secretion of IL-1β from primary BC induced by T cell cytokines and thymic stromal lymphopoietin (TSLP)." (PMID 34602858, 2021). "TSLP was significantly higher in the irradiated TME of patients with T1/2 stage tumours compared to those with T3/4 stage tumours." (PMID 33540635, 2021). "Tumour cell-derived TSLP reprograms myeloid DCs with Th2-polarising activity, and treatment of these mice with αTSLP antibodies not only diminished this effect but also significantly prolonged survival in humanised mice." (PMID 33401460, 2021). "They found that TSLP upregulation in the skin mediated a lasting tumor rejection reaction via CD4+ T-cell response in a Th2 inflammatory pathway." (PMID 34306760, 2021). "Recent studies have been focused on the context-dependent role of TSLP in a wide variety of cancers, which can either promote or inhibit tumour progression." (PMID 33652749, 2021).
tumor (continued). "Although the majority of experimental and human studies have demonstrated a protumorigenic role for TSLP, few groups have reported a tumor-suppressing role for TLSP in experimental and human cancer." (PMID 34440780, 2021). "TSLP produced by keratinocytes in cutaneous T cell lymphoma stimulates tumour growth by inducing Th2 cytokine in the tumour microenvironment." (PMID 33652749, 2021). "Nevertheless, the tumour suppressive role of TSLP-mediated inflammation has been reported in the mouse models of breast and skin cancers." (PMID 33652749, 2021). "Ki-67 staining showed that overexpression of GM-CSF and TSLP made tumor sustained proliferation even if arctigenin was administrated." (PMID 32887217, 2020). "TSLP promotes predominant Th2-type inflammation in different tumors and mediates pro-tumor but also anti-tumor functions." (PMID 33042121, 2020). "At difference with the anti-apoptotic function reported, in this model TSLP enhanced in vitro tumor cell apoptosis through caspase-3,−8, and−9 activation, and TSLP administration in xenograft models reduced tumor growth." (PMID 33042121, 2020). "It has been reported that 4T1 cells produce TSLP and the level of TSLP expression is correlated with tumor growth and metastasis." (PMID 32887217, 2020). "In another study, tumor cell-derived TSLP induced invasive and angiogenic gene expression profiles in alveolar macrophages." (PMID 33042121, 2020). "In one study, TSLP produced by myeloid cells after activation with tumor cell-derived IL-1α activated anti-apoptotic pathways in TSLPR-expressing tumor cells, through Bcl-2." (PMID 33042121, 2020). "Loss-of-function mutations in NOTCH lead to an impaired balance of tumor-protective/tumor-promoting inflammation by reducing the proinflammatory cytokine TSLP." (PMID 33003595, 2020). "Tumors from these transgenic mice had increased numbers of infiltrating CD4+ Th2 cells compared to WT mice, suggesting that in this model TSLP and Th2 cells exerted tumor-suppressive function in the context of a systemic Th2-polarized environment." (PMID 33042121, 2020). "In vivo TSLP functional inactivation either by silencing or by using TSLPR KO mice demonstrated the role of tumor-derived TSLP in inducing a metastases prone environment in the lungs." (PMID 33042121, 2020). "The function of TSLP in various types of tumors is tumor context dependent, and its role in BRCA is also controversial." (PMID 33193571, 2020). "Th2-independent mechanisms of TSLP in cancer have been reported in breast, lung, cervical, skin, and blood cancers, with pro- and anti-tumor effects, as detailed below." (PMID 33042121, 2020). "Then, this IL-1β is able to trigger CAFs to release thymic stromal lymphopoietin (TSLP), which is a key cytokine for Th2 pro-tumor immune response." (PMID 32635472, 2020). "On the other hand, both tumor-progressing and anti-tumor effects of TSLP have been demonstrated in diverse breast cancer studies." (PMID 32849527, 2020). "Several primary tumors and tumor cell lines have been described to produce alarmins as IL-25 and TSLP." (PMID 33233582, 2020). "Nevertheless, the current view of the field regarding the role of TSLP in cancer has been divided in terms of tumor-progressive or tumor-protective effects depending on the type of cancer being studied." (PMID 32849527, 2020). "TSLP allows the accumulation of CD11b+Gr1+ myeloid cells, which in turn, promote tumor growth by secreting Wnt ligands." (PMID 33003595, 2020). "Th2-dependent mechanisms of TSLP in cancer have been reported in pancreatic, breast, skin, gastric, and oropharyngeal cancers, with pro- and anti-tumor effects, as detailed below." (PMID 33042121, 2020). "Collectively, whereas a role for TSLP in cancer is firmly established, manipulation of its expression for therapeutic purposes will need further definition of its pro-tumor vs. anti-tumor function in the different tumor types." (PMID 33042121, 2020).